USP6NL (USP6 N-terminal like)
Description:
Acts as a GTPase-activating protein for RAB43, RAB5A and RAB30. Involved in receptor trafficking. In complex with EPS8 inhibits internalization of EGFR. Involved in retrograde transport from the endocytic pathway to the Golgi apparatus. Involved in the transport of Shiga toxin from early and recycling endosomes to the trans-Golgi network. Required for structural integrity of the Golgi complex.
Synonyms: RN-tre; KIAA0019; RNTRE; TRE2NL; USP6NL-IT1
Tractability: Antibody: its Gene Ontology location is reachable by antibodies, with high confidence. PROTAC: ubiquitination databases record sites on it.
Gene: Protein-coding gene on chromosome 10 (11,460,328 to 11,611,803, reverse strand). Ensembl gene ENSG00000148429.
Subcellular location: Golgi apparatus; Cytoplasmic vesicle
Pathways (Reactome):
Vesicle-mediated transport: Retrograde transport at the Trans-Golgi-Network
Gene Ontology:
Molecular function: GTPase activator activity; protein binding; small GTPase binding
Biological process: Golgi organization; plasma membrane to endosome transport; positive regulation of GTPase activity; regulation of cilium assembly; regulation of Golgi organization; retrograde transport, plasma membrane to Golgi; virion assembly
Cellular component: cytoplasmic vesicle; cytosol; plasma membrane; trans-Golgi network membrane; Golgi apparatus
Genetic constraint (gnomAD): Loss-of-function variants: 22 observed, 44.44 expected, observed/expected ratio (o/e) 0.5, 90% interval 0.35 to 0.71. The upper end of that interval is the gene's LOEUF score, 0.71, which puts it in group 2 of 6, group 1 being the genes least tolerant of losing a copy. Missense variants: 1,100 observed, 1,018.3 expected, observed/expected ratio (o/e) 1.08, 90% interval 1.03 to 1.13. Synonymous variants: 426 observed, 385.48 expected, observed/expected ratio (o/e) 1.11, 90% interval 1.02 to 1.2.
Homologues: Orthologues: chimpanzee USP6NL (99% identical), macaque USP6NL (97% identical), guinea pig USP6NL (86% identical), dog USP6NL (85% identical), rabbit USP6NL (85% identical), mouse Usp6nl (82% identical), rat Usp6nl (81% identical), pig USP6NL (79% identical), zebrafish usp6nl (48% identical), tropical clawed frog USP6NL (46% identical). Paralogues in human: TBC1D3K (19% identical), TBC1D3 (19% identical), TBC1D3C (19% identical), TBC1D3F (19% identical), TBC1D3B (19% identical), TBC1D3D (19% identical), TBC1D3E (19% identical), TBC1D3I (19% identical), TBC1D3G (19% identical), TBC1D3L (19% identical), TBC1D3H (19% identical), TBC1D26 (19% identical), and 33 more.
Diseases named in the same sentence as USP6NL in open-access papers:
USP6NL is named in the same sentence as 15 diseases in open-access papers, as found by Europe PMC text mining. Sharing a sentence is not in itself a finding about the gene and the disease. The quoted sentences say what the papers report.
breast cancer (5 papers, 2019 to 2022). A primary or metastatic malignant neoplasm involving the breast. "Breast cancer cells with high levels of USP6NL experienced delayed endocytosis and degradation of EGFR, activated AKT signaling." (PMID 35884836, 2022). "USP6NL levels are overexpressed in many breast cancer types, including triple-negative, which in turn leads to chronic AKT activation through phosphorylation." (PMID 35631131, 2022). "USP6NL is up-regulated and predicts a poor prognosis in human breast cancer (BC)." (PMID 31015802, 2019).
colorectal cancer (4 papers, 2019 to 2022). A primary or metastatic malignant neoplasm that affects the colon or rectum. "ECHDC3 has a role in fatty acid biosynthesis and has been found to have an increased expression in the brains of Alzheimer's patients while USP6NL is a GTPase-activating protein for Rabs and is up-regulated in several cancers, including breast and colorectal cancers." (PMID 35782544, 2022). "Therefore, we propose whether USP6NL is involved in colorectal cancer cell proliferation and metastasis through Wnt/β-catenin signaling." (PMID 31015802, 2019). "USP6NL, a key USP, plays a key role in the regulation of Wnt/β-Catenin signaling in colorectal cancer." (PMID 35884836, 2022).
Alzheimer disease (3 papers, 2022). A progressive, neurodegenerative disease characterized by loss of function and death of nerve cells in several areas of the brain leading to loss of cognitive function such as memory and language. "For example, the DMR gene USP6NL was a risk locus for Alzheimer’s disease, and the DMR gene CPLX1 was associated with cognitive resilience, nerve system development, and schizophrenia." (PMID 36344488, 2022). "For example, the DMP gene RIOK3 and the DMR gene USP6NL (overlapped DMR gene between case-control study and GAD vs OCD study) were the risk genes for Alzheimer’s disease." (PMID 36344488, 2022). "However, using an extended and even more recent list of GWAS results from the European Alzheimer’s disease DNA biobank (EADB) project published as preprint reveals several new connections, i.e. for ADAM17 & USP6NL (both miR-129-5p), CTSB & EED (miR-138-5p), and ANK3 & PLEKHA1 (miR-195-5p)." (PMID 36038535, 2022).
coronary artery disease (1 paper, 2019). "Besides Dendrin, only two proteins, junctional protein associated with coronary artery disease (JCAD) and USP6 N-terminal-like protein (USP6NL), contain two canonical ‘PPxY’ motifs separated by exactly two residues." (PMID 31486770, 2019).
fibromyalgia (1 paper, 2022). A chronic disorder of unknown etiology characterized by pain, stiffness, and tenderness in the muscles of neck, shoulders, back, hips, arms, and legs. "This suggests that these two critical SNPs and the gene USP6NL are particularly strongly associated with fibromyalgia cases." (PMID 36517845, 2022). "Two critical SNPs (rs10420798 and rs2499908) and the gene USP6NL (mapped to rs2499908) identified in the Pain Questionnaire cohort were replicated in the fibromyalgia cohort analysis." (PMID 36517845, 2022).
glioma (1 paper, 2022). A benign or malignant brain and spinal cord tumor that arises from glial cells (astrocytes, oligodendrocytes, ependymal cells). "Taken together, these results suggest USP6NL as an interesting potential to later predict EGFR overexpression or amplification in gliomas that may subsequently have a different phenotype than other glioma tumors." (PMID 35884836, 2022).
cancer (4 papers, 2020 to 2025). A tumor composed of atypical neoplastic, often pleomorphic cells that invade other tissues. "As for the subject ubiquitin specific peptidase 6 N-terminal like (USP6NL) mentioned in this study, this gene encoded a type of GTPase-activating protein which has been reported in past few years to participate in several cancers." (PMID 33054738, 2020). "Ubiquitin specific peptidase 6 N-terminal like (USP6NL) has been unmasked to be implicated in some human cancers." (PMID 33054738, 2020). "The USP6NL level, together with EGFR expression in human GBM tissue samples and cell lines associated with therapy resistance, tumor growth, and cancer invasion, were investigated." (PMID 35884836, 2022). "Thus, we deduced that USP6NL served a cancer-facilitating part in TNBC, suggesting it as an effective and useful biomarker for TNBC treatment." (PMID 33054738, 2020). "In addition, the protein and mRNA expression levels of USP6NL, pluripotency and cancer stem cell markers (CD44 and CD133), transcription factor (Nanog and SOX2), and efflux transporter ABCG2 were significantly overexpressed in the U87MG-R and T98G-R sphere compared with the parental control." (PMID 35884836, 2022). "This study provides novel insights into the USP6NL/EGFR axis that suppresses anticancer therapeutic responses, induces cancer invasiveness, and facilitates reduced sensitivity to TMZ treatment in GBM in an autolysosome-dependent manner." (PMID 35884836, 2022). "Our results provide novel insights into the probable mechanism through which USP6NL/EGFR signaling might suppress the anticancer therapeutic response, induce cancer invasiveness, and facilitate reduced sensitivity to temozolomide treatment in GBM in an autolysosome-dependent manner." (PMID 35884836, 2022).
tumor (4 papers, 2019 to 2025). "We demonstrated that the overexpression of USP6NL was strongly correlated with EGFR in the GBM tumor tissue and cell lines." (PMID 35884836, 2022). "USP6NL level in human CRC tissues and its association with tumor growth and metastasis were examined." (PMID 31015802, 2019). "In addition, the migratory, invasive, and tumor-initiating abilities of the cells were overtly reduced after USP6NL-knockdown in the U87MG-R and T98G-R cells compared with the control (scramble) transfected cells." (PMID 35884836, 2022). "Overexpression of USP6NL stabilizes EGFR, enhancing AKT signaling, tumor cell survival, and therapy resistance." (PMID 40565099, 2025). "Further, USP6NL was proved as the target of a tumor-inhibitor miR-142-3p, and LINC00689 augmented USP6NL expression by absorbing miR-142-3p." (PMID 33054738, 2020).
bacterial infection (1 paper, 2022). "We identified five genes—S100PBP, AKAP1, USP6NL, CDON and SULF2—in five different patient subgroups that have been associated with viral and/or bacterial infection in the literature." (PMID 36517845, 2022).
USP6NL also shares sentences with these, for which no sentence is quoted: dementia (1 paper); gastroenteropathy (1); glioblastoma (1); microcephaly (1); schizophrenia (1); triple-negative breast carcinoma (1).